RGPD4 (RANBP2 like and GRIP domain containing 4)
Synonyms: RGP4; DKFZp686P0288
Tractability: PROTAC: ubiquitination databases record sites on it.
Gene: Protein-coding gene on chromosome 2 (107,826,892 to 107,892,544, forward strand). Ensembl gene ENSG00000196862.
Subcellular location (Human Protein Atlas): Nuclear membrane; Vesicles
Gene Ontology:
Molecular function: SUMO transferase activity
Biological process: NLS-bearing protein import into nucleus; nuclear export
Cellular component: nuclear pore; Golgi apparatus
Genetic constraint (gnomAD): Loss-of-function variants: 75 observed, 74.29 expected, observed/expected ratio (o/e) 1.01, 90% interval 0.84 to 1.22. The synonymous counts are far from expectation, so gnomAD's model fits this gene poorly and the ratio says little. Missense variants: 867 observed, 1,039.8 expected, observed/expected ratio (o/e) 0.83, 90% interval 0.79 to 0.88. Synonymous variants: 286 observed, 361.35 expected, observed/expected ratio (o/e) 0.79, 90% interval 0.72 to 0.87.
Homologues: Orthologues: zebrafish ranbp3a (5% identical), Drosophila melanogaster RanBP3 (5% identical). Paralogues in human: RGPD3 (98% identical), RGPD1 (95% identical), RGPD2 (95% identical), RGPD5 (95% identical), RGPD6 (95% identical), RGPD8 (95% identical), RANBP2 (85% identical), RANBP3 (7% identical), RANBP3L (4% identical), RANBP1 (4% identical).
Diseases named in the same sentence as RGPD4 in open-access papers:
RGPD4 is named in the same sentence as 9 diseases in open-access papers, as found by Europe PMC text mining. Sharing a sentence is not in itself a finding about the gene and the disease. The quoted sentences say what the papers report.
Asperger’s syndrome (1 paper, 2022). "Serum proteomic analysis also provided evidence that RGPD4 expression showed male specificity in Asperger’s syndrome." (PMID 36158696, 2022).
interstitial lung disease (1 paper, 2022). A diverse group of lung diseases that affect the lung parenchyma. "Demographic and phenotypic characteristics of patients with SSc-associated interstitial lung disease (SSc-ILD) according to RGPD4-mutated status." (PMID 36158696, 2022). "Next, the animal model of SSc will be built upon the mouse, and the conditional knockout of RGPD4 in the mouse will be explored to confirm the pathogenicity to interstitial lung disease and detect the level of testosterone." (PMID 36158696, 2022).
ovarian serous cystadenocarcinoma (1 paper, 2022). A malignant serous cystic epithelial neoplasm arising from the ovary. "RANBP2-like and GRIP domain-containing 4 (RGPD4) is a protein-coding gene, and diseases associated with RGPD4 involve ovarian serous cystadenocarcinoma (OMIM 612707)." (PMID 36158696, 2022). "Additionally, proteomic analysis identified that RGPD4 determines the occurrence of ovarian serous cystadenocarcinoma, a type of cancer caused by high levels of androgen." (PMID 36158696, 2022). "RGPD4 is a protein-coding gene and is proved to be a candidate gene for ovarian serous cystadenocarcinoma in the OMIM database (612707)." (PMID 36158696, 2022).
infection (1 paper, 2024). The state of being infected such as from the introduction of a foreign agent such as serum, vaccine, antigenic substance or organism. "On the other hand, six targets produced positive Z-scores (>1.96) that indicated increased infection upon CRISPR targeting: RANBP2-like and GRIP domain containing 2 and 4 (RGPD2 and RGPD4), trinucleotide repeat containing adaptor 6B (TNRC6B), FAM21C, KIA00196 (aka, strumpellin), and zyxin." (PMID 38953638, 2024).
RGPD4 also shares sentences with these, for which no sentence is quoted: cancer (2 papers); metastatic melanoma (1); metastatic tumors (1); respiratory disease (1); systemic sclerosis (1).